ABO (ABO, alpha 1-3-N-acetylgalactosaminyltransferase and alpha 1-3-galactosyltransferase)
Description:
This protein is the basis of the ABO blood group system. The histo-blood group ABO involves three carbohydrate antigens: A, B, and H. A, B, and AB individuals express a glycosyltransferase activity that converts the H antigen to the A antigen (by addition of N-acetyl-alpha-D-galactosamine (GalNAc)) or to the B antigen (by addition of galactose (Gal)), whereas O individuals lack such activity and express the H antigen precursor unmodified. Catalyzes the transfer of GalNAc or Gal in an alpha1,3 linkage to the terminal Gal of all five types of naturally occurring H antigens, forming the antigenic structures of the A and B blood groups.
Synonyms: GTA; GTB; A3GALNT; A3GALT1; NAGAT
Target class: Enzyme
Safety:
Unwanted effects reported when the protein is acted on. In parentheses: how it was acted on, where the effect was seen, and who reports it.
angiotensin-converting enzyme inhibitors-induced cough (source: ClinPGx)
Cough (source: ClinPGx)
venous thrombosis (source: ClinPGx)
Gene: Protein-coding gene on chromosome 9 (133,233,278 to 133,276,024, reverse strand). Ensembl gene ENSG00000175164.
Subcellular location: Golgi apparatus, Golgi stack membrane; Secreted
Genetic constraint (gnomAD): Loss-of-function variants: 17 observed, 17.99 expected, observed/expected ratio (o/e) 0.94, 90% interval 0.65 to 1.42. The upper end of that interval is the gene's LOEUF score, 1.42, which puts it in group 5 of 6, group 1 being the genes least tolerant of losing a copy. Missense variants: 467 observed, 475.63 expected, observed/expected ratio (o/e) 0.98, 90% interval 0.91 to 1.06. Synonymous variants: 208 observed, 198.57 expected, observed/expected ratio (o/e) 1.05, 90% interval 0.94 to 1.17.
Homologues: Orthologues: macaque ABO (93% identical), rat Abo3 (72% identical), mouse Abo (70% identical), rat Abo2 (70% identical), dog ABO (69% identical), tropical clawed frog abo.2 (57% identical), tropical clawed frog abo.3 (53% identical). Paralogues in human: GBGT1 (42% identical), A3GALT2 (36% identical), GLT6D1 (25% identical).
Diseases named in the same sentence as ABO in open-access papers:
ABO is named in the same sentence as 301 diseases in open-access papers, as found by Europe PMC text mining. Sharing a sentence is not in itself a finding about the gene and the disease. The quoted sentences say what the papers report.
COVID-19 (169 papers, 2020 to 2026). A disease caused by infection with severe acute respiratory syndrome coronavirus 2. "This study provides a comprehensive analysis of the interplay between ABO blood group phenotypes and key virological and clinical features of COVID-19, including SARS-CoV-2 RNAemia, spike gene mutations, variant distribution, and thrombotic complications." (PMID 40872268, 2025). "Previous studies have reported that the susceptibility to coronavirus disease 2019 (COVID-19) is related to ABO blood group, but the relationship with Rh phenotype and MN blood group is unknown." (PMID 38241306, 2024). "The association remained significant after adjustment for demographic factors and for the main genetic loci for susceptibility to and severity of COVID-19 at ABO and LZFTL1, respectively (p = 0.001)." (PMID 41596638, 2026). "It was shown that the ABO protein is a causative risk factor for severe COVID-19 symptoms and predisposition to COVID-19." (PMID 40002898, 2025). "Specific gene variants, including those within the HLA-DRB, HLA-B, and ABO blood group systems, have been linked to varying degrees of susceptibility and severity of COVID-19." (PMID 41012626, 2025). "With the pervasiveness of COVID-19 and the call for proper risk stratification, the present study has beenconducted to find the association between ABO and Rh blood groups with susceptibility and severity of COVID-19 within a diversepopulation." (PMID 40978629, 2025). "We observed that for COVID-19 susceptibility, the 3p21.31 locus and the ABO locus contributed to both susceptibility and long COVID with a high posterior probability." (PMID 40399555, 2025). "In this study, we examine the relationship between ABO blood group phenotypes and the pathogenesis of COVID-19 by analyzing SARS-CoV-2 RNAemia, spike gene mutational profiles, variant lineage distribution, and the incidence of thrombotic events." (PMID 40872268, 2025). "An examination of the prevalence of SARS-CoV-2 spike gene mutations across ABO blood groups in COVID-19 patients was conducted, focusing on mutations including N501Y, D614G, K417N, N440K, E484K, P681R, T547K, R346T–R346Y, H69del, and V70del." (PMID 40872268, 2025). "As the results of previous studies and the present research revealed, there is a marked association between ABO blood type and there is a Rrisk of infection with COVID-19." (PMID 39045258, 2024). "Early GWAS of COVID-19 patients provided a biologically plausible mechanism for this proposed phenomenon by identifying a reproducible association of susceptibility to COVID-19 with locus 9q34.2, which coincides with the ABO locus." (PMID 40012912, 2024). "Multivariate logistic regression analysis of ABO blood type, Rh phenotype, and MN blood type associated with susceptibility to COVID-19*." (PMID 38241306, 2024). "Further studies are required to determine the relationship between ABO blood types and susceptibility against COVID-19." (PMID 39045258, 2024). "Despite the arrival of the pandemic deeply impacted donor recruitment routine activity, blood donor registries have been immediately exploited to identify possible correlations of the ABO blood group with COVID-19 severity and risk of infection." (PMID 37988390, 2023). "There are multiple associations between the different blood groups of the ABO and RhD system with the incidence of diseases, like certain carcinomas and COVID-19." (PMID 36984806, 2023). "ABO, a protein-coding gene involved in blood group systems biosynthesis and coagulation, is a well-known COVID-19 risk gene." (PMID 37636041, 2023). "There are multiple associations between the different blood groups (ABO and RhD) and the incidence of oxidative stress-related diseases, such as certain carcinomas and COVID-19." (PMID 36984806, 2023).
COVID-19 (continued). "High levels of circulating GCNT4, RAB14, C1GALT1C1, CD207 and ABO have also been previously suggested to be causally associated with an increased risk of suffering from critical COVID-19, with comparable odds ratios varying from 1.12 to 1.35." (PMID 37958866, 2023). "In a subset of 79 children, a genetic analysis was carried out to evaluate the role of common COVID-19 genetic risk factors (chromosome 3 cluster; ABO-blood group system; FUT2, IFNAR2, OAS1/2/3, and DPP9 loci)." (PMID 36873632, 2023). "Epidemiological studies among different populations suggested different impacts of ABO and Rh antibodies on the COVID-19 susceptibility." (PMID 36727032, 2023). "The strongest association signals were localized on or near the ABO gene (index SNP: rs11244061 for severe COVID-19 and COVID-19 hospitalization; rs550057 for SARS-CoV-2 infection) at locus 9q34.2." (PMID 37085521, 2023). "Recent research on blood groups and SARS-COV-2 infection have reported similar interactions between ABO incompatibility and decreased risk of COVID-19 transmission, suggesting neutralization by naturally occurring anti-ABO antibodies." (PMID 37099490, 2023). "The first genome-wide association study (GWAS) of COVID-19 reported two severity-associated loci in Italians and Spanish: the 3p21.31 locus containing several immune genes and ABO locus determining ABO blood groups." (PMID 36531218, 2022). "Another important aspect of association between specific ABO types and increased COVID-19 severity is the genomic aspect of each group." (PMID 36714134, 2022). "In conclusion, the AA genotype of ABO rs657152 and blood type A were associated with a considerably increased frequency of COVID-19 mortality." (PMID 36419842, 2022). "Our study aimed to investigate the association between the ABO blood group and the outcomes of COVID-19, including the risk of infection, clinical presentation, and disease severity among hospitalized patients." (PMID 36013335, 2022). "This study is a comprehensive study to identify a strong association between ABO blood groups and the allele frequency of ABO rs657152 and COVID-19 mortality in Iran." (PMID 36419842, 2022). "In line with our findings, several studies have shown that the ABO rs657152 A allele is significantly correlated with COVID-19 severity, but in the previous 2 studies, this relationship was not shown." (PMID 36419842, 2022). "The ABO gene locus was also found in six different research studies and is associated with an effect on COVID-19 susceptibility." (PMID 35351987, 2022). "The study aimed to determine the association of ABO, Rhesus (D) and P1 blood groups with COVID-19 susceptibility in Taif city, Western Saudi Arabia." (PMID 37092112, 2022). "The identification of biological markers including ABO, D and P1 blood groups for predicting high risk individuals to COVID-19 through simple and rapid tests is important." (PMID 37092112, 2022). "Based on the top-ranked V2G score for rs505922, we prioritized ABO as a potential causal gene contributing susceptibility to severe COVID-19." (PMID 35172892, 2022). "The association signal at locus 9q34.2 coincided with ABO locus, suggesting the role of ABO blood type in COVID-19 severity." (PMID 36204639, 2022). "Here, we assessed the association between COVID-19 severity among Ghanaians with their immune profiles and ABO blood groups." (PMID 36184636, 2022). "The rs8176719 (-/C) polymorphism in the ABO gene was evaluated in 3 studies (2 articles) about COVID-19 development and 4 studies (3 articles) regarding disease severity." (PMID 35793369, 2022). "The ABO gene responsible for determining blood type has been suggested to be associated with the severity of COVID-19." (PMID 35062298, 2022). "Gene ABO, mapped by the locus rs495828 in 9q34.2 region, was reported to be associated with COVID-19, CAD, OBE and HTN (Covid-19 Host Genetics Initiative., 2021)." (PMID 36187959, 2022).
COVID-19 (continued). "In summary, this study demonstrated that the rs512770 T/C, and rs8176740 T/A polymorphisms of the ABO gene were associated with an increased risk of developing COVID-19 in a Mexican population." (PMID 35454075, 2022). "Our data suggested that the ABO rs512770 T/C and rs8176740 T/A polymorphisms increased the risk of developing COVID-19 and the plasma concentration of platelets." (PMID 35454075, 2022). "This study aimed to associate genetic variants in the SLC6A20, LZTFL1, CCR9, FYCO1, CXCR6, XCR1, and ABO genes with the risk of severe forms of COVID-19 in Amazonian Native Americans, and to compare the frequencies with continental populations." (PMID 35455670, 2022). "Herein, we performed ABO typing on 373 Saudi patients with confirmed SARS-CoV-2 infection and conducted association analysis between ABO blood group phenotypes and COVID-19." (PMID 34978705, 2022). "In this study, out of 1238 variant previously reported to be association with susceptibility and severity of COVID-19, we confirmed 49 variants, corresponding to 18 independent loci, including 3p21.31 locus, ABO, IFNAR2, TNF, APOE, and FOXP4-AS1 gene." (PMID 36531218, 2022). "The association between mortality rate of COVID-19 and the frequency of ABO rs657152 was significant." (PMID 36419842, 2022). "This study aimed to determine if there is an association between ABO, Rhesus (D) and P1 blood group blood type with the susceptibility of COVID-19 in Taif city, Western Saudi Arabia." (PMID 37092112, 2022). "The possible association of COVID-19 severity with ABO blood groups certainly ranks among the most investigated in the field of genetics of infectious diseases." (PMID 35364749, 2022). "We studied six polymorphisms located in the ABO gene (rs651007 T/C, rs579459 T/C, rs8176740 T/A, rs8176746 A/C, rs495828 T/G, and rs512770 T/C) in patients with COVID-19." (PMID 35454075, 2022). "Instead, we confirmed several other variants in the ABO locus when comparing all COVID-19 cases with general Chinese population." (PMID 36531218, 2022). "Previously reports that included a genome wide association study (GWAS) showed that some ABO SNPs, such as rs657152 A/C and rs505922 C/T, were associated with a major risk of infection, severity, and mortality in patients with COVID-19." (PMID 35454075, 2022). "A recent replication analysis of reported COVID-19 genetic associations with eight phenotypes found that the lead ABO SNP, rs505922, replicated in all four susceptibility phenotypes and one severity phenotype." (PMID 36204639, 2022). "There is much to be done to understand the role of ABO and its association to COVID-19 severe phenotypes." (PMID 35096865, 2021). "By conducting a GWAS and extracting the SNPs in the ABO gene, we have provided further insight into the genetic mechanisms associated with COVID-19 disease severity and the possible link to allelic variants and COVID-19 critical phenotypes." (PMID 35096865, 2021). "There are three studies which investigated the association of Rh blood groups in addition to ABO with COVID-19; however, in the statistical analysis, ABO and Rh have been considered separately." (PMID 38624675, 2021). "The multivariate logistic regression analysis demonstrated the association of ABO blood type as well as circulating anti-A antibodies and anti-B antibodies as well as A and B antigens, in association with critical COVID-19 hospital presentation." (PMID 35096865, 2021). "From these and further epidemiological studies using different populations the association between distinct ABO blood groups and COVID-19-linked hospitalization is well established." (PMID 35178379, 2021). "At p<1 × 10–5 (Bonferroni corrected for the ~3000 phenotypes in the Open Targets Genetics portal), most of the variants exhibited associations with haematological indices, with some, like the ABO signal, also associated with other COVID-19-relevant phenotypes." (PMID 34402426, 2021).
COVID-19 (continued). "An additional protein that was supported by both MR and genetic colocalisation tests was ABO, reported in several published genome-wide association studies (GWAS) of COVID-19." (PMID 34402426, 2021). "The ABO gene is associated with a number of other traits including risk factors for COVID-19 morbidity and mortality." (PMID 35096865, 2021). "We propose similar work shall be carried out on a larger sample to have a clearer insight into the association between ABO/Rh-D blood types and susceptibility to COVID-19." (PMID 33437242, 2021). "The combination of genetic and serological evidence of the involvement of the ABO blood groups and ABO gene allelic associations with COVID-19 severity provides a unique opportunity to study host genomics to the interindividual phenotypic variability." (PMID 35096865, 2021). "This study is the first study to combine genetic and serological evidence of the involvement of the ABO blood groups and the ABO gene allelic associations with COVID-19 severity within the Middle Eastern population." (PMID 35096865, 2021). "A study on COVID-19 demonstrated a cross-replicating association signal at locus 9q34.2, which coincides with the ABO blood group locus." (PMID 34905588, 2021). "In further analysis, the associations between combination of the ABO and Rh phenotypes and susceptibility to COVID-19 were investigated." (PMID 38624675, 2021). "The polygenic (pan) and cis-Mendelian randomisation analyses showed consistent associations of genetically predicted ABO protein with several COVID-19 phenotypes." (PMID 34402426, 2021). "After the outbreak of the COVID-19 infection, the likelihood of association between ABO blood groups and the susceptibility to COVID-19 exposure has been reported in patients from three hospitals in Wuhan, Shenzhen, and China." (PMID 33401440, 2021). "Our data strengthen the evidence for a role for ABO in COVID-19 susceptibility and severity and is notable given the reported links between COVID-19 and blood clotting complications that has now been associated with C5a activity." (PMID 35096865, 2021). "A candidate gene analysis approach was conducted from a GWAS where we examined 240 single nucleotide polymorphisms (SNPs) (position in chr9: 136125788-136150617) in the ABO gene, in association with critical COVID-19 hospital presentation." (PMID 35096865, 2021). "Genetically predicted ABO concentration was associated with risk in four out of seven COVID-19 outcomes." (PMID 34402426, 2021). "Further investigation of cross-phenotype SNPs associated with both severe COVID-19 and other human traits demonstrated colocalization of the GWAS signal at the ABO locus with plasma protein levels of a reported receptor of SARS-CoV-2, CD209 (DC-SIGN)." (PMID 34001247, 2021). "In the wake of the COVID-19 pandemic, research indicates that the COVID-19 disease susceptibility varies among individuals depending on their ABO blood groups." (PMID 34967364, 2021). "When adding the naïve controls (n = 954; Methods section), the rs2109069 in DPP9 gene and rs657152 in ABO gene were significantly associated with COVID-19 severity (for rs2109069 A allele: P = 0.0042, OR = 1.33; for rs657152 A allele: P = 0.0017, OR = 1.27)." (PMID 34465742, 2021). "There are only two studies which investigated the association of Rh blood groups in addition to ABO with COVID-19; however, in the statistical analysis ABO and Rh blood groups have been considered separately." (PMID 38624675, 2021). "In our study, we observed that the intron variant rs8176725 of ABO determined an increase in histo-blood group ABO system transferase expression and correlated negatively with COVID-19 cases." (PMID 33981715, 2021). "First, we showed that genetically predicted circulating ABO protein was associated with COVID-19 susceptibility and severity and the lead ABO signal was associated strongly with plasma concentrations of soluble CD209." (PMID 34402426, 2021).